NYAP1 (neuronal tyrosine phosphorylated phosphoinositide-3-kinase adaptor 1)
Description:
Activates PI3K and concomitantly recruits the WAVE1 complex to the close vicinity of PI3K and regulates neuronal morphogenesis.
Synonyms: C7orf51; FLJ37538; formerly KIAA1486L
Tractability: PROTAC: its protein half-life has been measured.
Gene: Protein-coding gene on chromosome 7 (100,483,605 to 100,494,802, forward strand). Ensembl gene ENSG00000166924.
Subcellular location (Human Protein Atlas): Vesicles; Golgi apparatus
Gene Ontology:
Biological process: neuron projection morphogenesis; phosphatidylinositol 3-kinase/protein kinase B signal transduction
Genetic constraint (gnomAD): Loss-of-function variants: 20 observed, 43.71 expected, observed/expected ratio (o/e) 0.46, 90% interval 0.32 to 0.67. The synonymous counts are far from expectation, so gnomAD's model fits this gene poorly and the ratio says little. Missense variants: 1,145 observed, 1,061.2 expected, observed/expected ratio (o/e) 1.08, 90% interval 1.03 to 1.13. Synonymous variants: 571 observed, 463.86 expected, observed/expected ratio (o/e) 1.23, 90% interval 1.15 to 1.32.
Homologues: Orthologues: chimpanzee NYAP1 (99% identical), macaque NYAP1 (98% identical), pig NYAP1 (95% identical), guinea pig NYAP1 (93% identical), rat Nyap1 (92% identical), mouse Nyap1 (91% identical), rabbit NYAP1 (88% identical), tropical clawed frog nyap1 (43% identical). Paralogues in human: NYAP2 (28% identical).
Diseases named in the same sentence as NYAP1 in open-access papers:
NYAP1 is named in the same sentence as 4 diseases in open-access papers, as found by Europe PMC text mining. Sharing a sentence is not in itself a finding about the gene and the disease. The quoted sentences say what the papers report.
Alzheimer disease (1 paper, 2025). A progressive, neurodegenerative disease characterized by loss of function and death of nerve cells in several areas of the brain leading to loss of cognitive function such as memory and language. "Bridging integrator 1 (BIN1), triggering receptor expressed on myeloid cells 2 (TREM2), and zinc finger CW-type (ZCWPW1)/PWWP domain containing 1 (NYAP1) were identified in both all-cause dementia and Alzheimer's disease." (PMID 40949174, 2025).
prostate carcinoma (1 paper, 2020). A carcinoma that arises from epithelial cells of the prostate gland. "Future studies to evaluate the mechanistic role of nYAP1 in prostate cancer resistance to chemotherapy using our cells and TMAs are imperative to help deepen on our understanding of these processes." (PMID 32293349, 2020).
cancer (1 paper, 2020). A tumor composed of atypical neoplastic, often pleomorphic cells that invade other tissues. "The expression of several steroid receptors and Hippo pathway–related proteins, including nYAP1, were up- and downregulated in the residual cancer and stromal cells in patients with PCa who underwent CHT compared with those treated with NNA and NHT." (PMID 32293349, 2020). "Previous studies have described the mechanistic effects of nYAP1 on its regulators, including TEADs, VGLL, p160 family protein, and ERK-RSK signaling, during cancer development." (PMID 32293349, 2020). "The nYAP1 immunoreactivity score of residual cancer cells in the CHT group was the highest, although no statistical differences were found among the three groups." (PMID 32293349, 2020).
NYAP1 also shares sentences with these, for which no sentence is quoted: dementia (1 paper).